PHGDH (phosphoglycerate dehydrogenase)
Diseases named in the same sentence as PHGDH in open-access papers (continued):
Sharing a sentence is not in itself a finding about the gene and the disease.
astrocytoma (2 papers, 2013 to 2014). "In this study, we showed that PHGDH was robustly expressed in a large proportion of astrocytomas, and its expression levels increased with tumor grade." (PMID 23229761, 2013).
brain ischemia (2 papers, 2025 to 2026). Diminished or absent blood supply to the brain caused by obstruction (thrombosis or embolism) of an artery resulting in neurologic damage. "In the present study, we documented a significant suppression of PHGDH-dependent serine metabolic pathways after cerebral ischemia-reperfusion, coupled with a substantial decrease in PHGDH expression." (PMID 41344159, 2025). "Our findings demonstrate that PHGDH displays predominant expression in brain astrocytes and undergoes time-dependent alterations in reactive astrocytes following cerebral ischemia-reperfusion." (PMID 41344159, 2025). "Specifically, targeted knockdown of PHGDH expression in astrocytes substantially exacerbates pathological damage and neurological deficits post cerebral ischemia-reperfusion." (PMID 41344159, 2025). "In summary, targeted PHGDH overexpression and activation hold promise as a potential key target for the treatment of cerebral ischemia-reperfusion injury in the future." (PMID 41344159, 2025). "This study reveals that the serine de novo synthesis pathway, with PHGDH as the key enzyme, is significantly downregulated after cerebral ischemia-reperfusion." (PMID 41344159, 2025). "Therefore, the current investigation aims to elucidate the molecular mechanisms by which PHGDH-mediated downregulation of serine metabolism initiates astrocyte - associated oxidative stress, pyroptosis, and subsequently exacerbates neuronal injury following cerebral ischemia-reperfusion." (PMID 41344159, 2025). "In summary, this study integrates transcriptomic, metabolomic, and functional experimental data to elucidate the role of PHGDH-mediated serine de novo synthesis in regulating astrocyte oxidative stress and pyroptosis following cerebral ischemia-reperfusion." (PMID 41344159, 2025). "In conclusion, downregulation of PHGDH in astrocytes post cerebral ischemia-reperfusion predominantly drives astrocyte pyroptosis via oxidative stress, resulting in the release of pro-inflammatory cytokines (e.g., IL-1β and IL-18) and subsequent exacerbation of ischemia-reperfusion injury." (PMID 41344159, 2025). "These novel insights into the role of PHGDH may inform the development of targeted therapeutic strategies for cerebral ischemia-reperfusion." (PMID 41344159, 2025). "We envision that drugs targeting PHGDH could be developed in future studies for the treatment of cerebral ischemia-reperfusion injury." (PMID 41344159, 2025). "Therefore, targeting PHGDH is effective and safe in animal models, and it can serve as a potential therapeutic target for cerebral ischemia-reperfusion injury." (PMID 41344159, 2025).
cholangiocarcinoma (2 papers, 2025 to 2026). A carcinoma that arises from the intrahepatic biliary tree (intrahepatic cholangiocarcinoma) or from the junction, or adjacent to the junction, of the right and left hepatic ducts (hilar cholangiocarcinoma). "Targeting these metabolic pathways (such as GLS1, ARG1, PHGDH, IDO1, etc.)may restore the function of immune cells, inhibit tumor progression, and provide new strategies for the treatment of cholangiocarcinoma." (PMID 41513616, 2026).
Cognitive impairment (2 papers, 2022 to 2025). Abnormal cognition is characterized by deficits in thinking, reasoning, or remembering. "Further, PHGDH has been found to contribute to the development of cognitive impairment." (PMID 37008043, 2022). "Research showed that when PHGDH agonists are administered to patients with refractory epilepsy, both the duration of epileptic seizures and the severity of seizures are reduced, with no adverse reactions such as cognitive impairment reported." (PMID 41344159, 2025).
developmental delay (2 papers, 2021 to 2024). "A deficiency of PHGDH causes psychomotor developmental delay." (PMID 38736872, 2024).
dilated cardiomyopathy (2 papers, 2023 to 2026). Cardiomyopathy which is characterized by dilation and contractile dysfunction of the left and right ventricles. "PHGDH knockdown accelerated while PHGDH overexpression delayed the senescence of HUVECs, and vascular endothelium-specific overexpression of PHGDH prevented dilated cardiomyopathy, improved cardiac function, promoted endothelial function and slowed down cellular senescence in aged mice." (PMID 41561820, 2026).
epilepsy (2 papers, 2025). A brain disorder characterized by episodes of abnormally increased neuronal discharge resulting in transient episodes of sensory or motor neurological dysfunction, or psychic dysfunction. "Increasing evidence links PHGDH deficiency with (drug‐resistant) epilepsy." (PMID 40616775, 2025). "Increasing evidence links deficiency or malfunctioning of the enzyme phosphoglycerate dehydrogenase (PHGDH), which converts 3‐phosphoglycerate to generate serine and the neurotransmitter glycine, with (drug‐resistant) epilepsy." (PMID 40616775, 2025). "We also observed that epilepsy-associated genes PDCC10, PHGDH, PSAT1, and TBC1D24 showed higher expression levels in SOZ compared with PZ." (PMID 39541170, 2025). "Moreover, we show that clioquinol has PHGDH‐dependent antiseizure activity as well as anti‐inflammatory properties in vivo using various zebrafish and mouse epilepsy models." (PMID 40616775, 2025). "We screened a drug repurposing library for PHGDH activators and assessed their antiseizure and anti‐inflammatory properties using various zebrafish and mouse epilepsy models and explored the mechanistic consequences of activating PHGDH in a cell line, in astrocytes, and in zebrafish heads." (PMID 40616775, 2025).
esophageal cancer (2 papers, 2015 to 2024). A primary or metastatic malignant neoplasm involving the esophagus. "Proliferation of T.T. cells, an esophageal cancer cell line with PHGDH copy number gain, has been shown previously to be sensitive to stable knockdown of PHGDH expression." (PMID 25926973, 2015).
Infertility (2 papers, 2020 to 2024). "At present, the literature relating to PHGDH in spermatogenesis is quite limited and many questions, particularly related to mechanisms, still remain to be elucidated regarding the mechanisms underlying varicocele-related infertility." (PMID 32664979, 2020).
injury (2 papers, 2025). Damage inflicted on the body as the direct or indirect result of an external force, with or without disruption of structural continuity. "PHGDH degradation suppresses SSP and glutathione production, thereby exacerbating DILI and cholestatic liver injury." (PMID 39962071, 2025).
Insulin resistance (2 papers, 2020 to 2025). Increased resistance towards insulin, that is, diminished effectiveness of insulin in reducing blood glucose levels. "Among these DMRs, SREBF1, HOXA5, CPT1A, LPIN1, and PHGDH have established roles in adipose tissue biology and insulin resistance." (PMID 33243154, 2020).
ischemia (2 papers, 2025). A hypoperfusion of the BLOOD through an organ or tissue caused by a PATHOLOGIC CONSTRICTION or obstruction of its BLOOD VESSELS, or an absence of BLOOD CIRCULATION. "Nevertheless, after I/R, overexpression of PHGDH exerted a prominent neuroprotective effect on neurological function, which in turn alleviated ischemia/reperfusion-induced damage and attenuated the development of inflammation." (PMID 41344159, 2025).
ischemic stroke (2 papers, 2025 to 2026). A stroke disorder caused by obstruction of blood flow to the brain, due to thrombotic (local blood clot formation) or embolic (due to a blood clot or other material traveling from another site) event. "PHGDH inhibition with NCT-503 did not affect acute neuronal injury but worsened sensorimotor and cognitive functional outcomes after ischemic stroke." (PMID 42064802, 2026).
macular degeneration (2 papers, 2022 to 2025). Loss of vision in the central portion of the retina (macula), secondary to retinal degeneration. "There is currently very limited direct evidence that amino acids serve as mitochondrial fuel in the retina, although gene mutations in endogenous serine synthetic enzyme phosphoglycerate dehydrogenase (PHGDH) are associated with macular degeneration." (PMID 36420952, 2022).
macular telangiectasia type 2 (2 papers, 2021 to 2024). Macular telangiectasia type 2 is a rare neurovascular degenerative retinal disease. "This same enzyme PHGDH has been genetically linked with macular telangiectasia type 2 (MacTel), a rare eye disease characterized by pathological blood vessel growth within the retina with underlying defective serine biosynthesis." (PMID 39335451, 2024). "Mutations in PHGDH have been identified as the cause of a rare neurodegenerative degenerative retinal disease, macular telangiectasia type 2 (MacTel), which results in photoreceptor degeneration in humans." (PMID 34684470, 2021).
mastitis (2 papers, 2019 to 2025). Inflammation of breast tissue during lactation or postpartum due to an obstructed duct or infection. "The three prioritized genes for both Trait_GWAS and EBV_GWAS datasets (PHGDH, SLC1A4, and CSN3) play relevant roles in biological processes associated with milk production, cheese production, and resistance to mastitis." (PMID 41306553, 2025).
medulloblastoma (2 papers, 2025 to 2026). A malignant, invasive embryonal neoplasm arising from the cerebellum. "Taken together, our findings reveal MYC-dependent sensitivity to PHGDH inhibition in medulloblastoma cells resulting in reduced growth and proliferation." (PMID 39377369, 2025). "Critically, in primary human medulloblastomas, increased PHGDH expression correlated strongly with both MYC amplification and poorer clinical outcomes." (PMID 39377369, 2025). "Together our findings support the clinical relevance of PHGDH as a therapeutic target in medulloblastoma, with higher expression observed in MYC-amplified MBGRP3 defining a patient population that would most benefit from PHGDH perturbation." (PMID 39377369, 2025). "To specifically validate PHGDH as a therapeutically actionable target in MYC-driven MB, we assessed its protein expression in a large representative cohort of primary medulloblastomas (n = 183) and normal cerebellar controls (n = 9)." (PMID 39377369, 2025).
metabolic syndrome (2 papers, 2021 to 2023). A cluster of metabolic risk factors for CARDIOVASCULAR DISEASES and TYPE 2 DIABETES MELLITUS. "In other genes, including SLC7A11 and PHGDH, 17 urate-associated CpGs are associated with conditions defining metabolic syndrome, suggesting that these CpGs may represent a blood DNA methylation signature of cardiometabolic risk factors." (PMID 34887389, 2021). "Our study showed that the expression levels of oxidoreductases, including d-3-phosphoglycerate dehydrogenase (PHGDH) and malate dehydrogenase (MDH1), were also decreased at the symptomatic stage of the metabolic syndrome, which may further worsen oxidative stress." (PMID 37107219, 2023).
ovarian tumors (2 papers, 2022 to 2024). "PHGDH has been identified as a potential antitumor therapeutic target, showing increased expression in primary ovarian tumors." (PMID 38733440, 2024).
pancreatic ductal adenocarcinoma (2 papers, 2023 to 2024). An infiltrating adenocarcinoma that arises from the epithelial cells of the pancreas. "PHGDH expression in pancreatic ductal adenocarcinoma under conditions of serine depletion exhibits an increase consistent with the cellular growth pattern." (PMID 38945960, 2024).
rectal cancer (2 papers, 2022). A primary or metastatic malignant neoplasm that affects the rectum. "Additionally, overall survival (OS) was plotted using patient-derived data from rectum cancer patients and made the distinction between low and high expression of PHGDH, PSAT1 and PSPH." (PMID 36291844, 2022).
sarcopenia (2 papers, 2024 to 2025). Progressive decline in muscle mass due to aging which results in decreased functional capacity of muscles. "The role of the remaining eight key genes (ALDH1L, EME1, PYGL, NNMT, PHGDH, CD52, CD3D, and ESM1) in COVID-19 and sarcopenia has been less studied, emphasizing their importance in future research." (PMID 38978778, 2024).
small cell lung carcinoma (2 papers, 2022 to 2024). Small cell lung cancer (SCLC) is a highly aggressive malignant neoplasm, accounting for 10-15% of lung cancer cases, characterized byrapid growth, and early metastasis. "Proteomic analysis of six small cell lung carcinoma (SCLC) and six pulmonary carcinoid tumor (PCT) tissues indicated that PHGDH overexpression is significantly associated with cancer metabolism and poor overall survival (OS)." (PMID 36699468, 2022).
alcoholic fatty liver disease (1 paper, 2021). Lipid infiltration of the hepatic parenchymal cells that is due to alcohol abuse. "Bioinformatic approaches have indicated the downregulation of PHGDH in the liver of patients with non-alcoholic fatty liver disease and alcoholic hepatitis patients." (PMID 34684470, 2021).
aneurysm (1 paper, 2021). Bulging or ballooning in an area of an artery secondary to arterial wall weakening. "PHGDH encodes an enzyme that is involved in L-serine synthesis, and has been shown to have decreased expression in aneurysm tissue." (PMID 34203780, 2021).
aortic aneurysm (1 paper, 2019). A ruptured aneurysm located in the wall of the proximal portion of the descending aorta proceeding from the arch of the aorta. "We see only one protein overlapping with ‘aortic aneurysm’ for the RXFP3 ‘stress’ dataset, namely PHGDH (Phosphoglycerate Dehydrogenase) and none for the RXFP3 ‘control’ set." (PMID 31794429, 2019).
asthenospermia (1 paper, 2020). "First, we discovered that testicular protein PHGDH was down-regulated in varicocele male adults with asthenospermia (Supplementary File1), due to the small sample size, we chose to verify the results in experimental rat varicocele model." (PMID 32664979, 2020).
Cachexia (1 paper, 2021). Severe weight loss, wasting of muscle, loss of appetite, and general debility related to a chronic disease. "Importantly, using our ESCC model of cachexia, we successfully identified PHGDH as a target of P4HB in cachexia‐associated muscle wasting." (PMID 33732415, 2021).
cardiomyopathies (1 paper, 2025). "PHGDH overexpression was previously shown to repress the calcification of human coronary artery vascular smooth muscle cells and variants of the OBSCN gene have been associated with different cardiomyopathies." (PMID 41159936, 2025).
clear cell renal cell carcinoma (1 paper, 2020). "Our previous studies revealed that PHGDH gene amplification was associated with poor overall survival in clear cell renal cell carcinoma (ccRCC) and that metabolic reprogramming of serine synthesis through PHGDH recruitment allowed ccRCC cells to survive in unfavorable environments." (PMID 32386122, 2020).
cleft lip (1 paper, 2023). Congenital defect in the upper lip where the maxillary prominence fails to merge with the merged medial nasal prominences. "In child 4 with unilateral cleft lip and palate, we identified an autosomal homozygous pattern of inheritance in the phosphoglycerate dehydrogenase (PHGDH) gene (rs143340742) located on chr.1: 120279876 (c.932C > T)." (PMID 36980938, 2023).
cognitive decline (1 paper, 2025). "In the same study, a sequential increase of PHGDH expression in patients with early and late AD pathology was reported in hippocampus and prefrontal cortex: the increase in PHGDH expression correlated with progression of clinical symptoms and worsening cognitive decline." (PMID 40761926, 2025).
colonic adenomas (1 paper, 2013). "Upregulation of phosphoglycerate dehydrogenase (PHGDH) as judged by IHC, an enzyme upstream of serine biosynthesis also occurs in our intestinal tumors (unpublished data) and to a lesser extent in the colonic adenomas." (PMID 23935891, 2013).
colorectal adenocarcinoma (1 paper, 2020). The most common type of colorectal carcinoma. "Kaplan–Meier survival analysis showed a significantly shorter overall survival in colorectal adenocarcinoma patients with high ILF3, PHGDH, or SHMT2 gene expression." (PMID 31772275, 2020).
diffuse large B-cell lymphoma (1 paper, 2020). "We first investigated the expression of SBP genes, PHGDH and PSAT1, in BL and another type of aggressive B-cell malignancy, diffuse large B-cell lymphoma (DLBCL), using a publicly available dataset." (PMID 32138178, 2020).
endometrial adenocarcinoma (1 paper, 2022). "In addition, PHGDH was expressed in prostatic adenocarcinoma, invasive ductal carcinoma of the breast, endometrial adenocarcinoma and ovarian adenocarcinoma." (PMID 35204409, 2022).
endometrioid carcinoma (1 paper, 2023). "PHGDH expression was also higher in serous endometrial carcinoma than in endometrioid carcinoma (P < 0.001)." (PMID 36803157, 2023).
esophageal squamous cell carcinoma (1 paper, 2024). Esophageal squamous cell carcinoma (ESCC) is a type of esophageal carcinoma (EC) that can affect any part of the esophagus, but is usually located in the upper or middle third. "The findings revealed a significant association between PHGDH expression and the pathological stage of esophageal squamous cell carcinoma." (PMID 38945960, 2024). "A correlation between PHGDH expression and metastasis stage has been reported in patients with esophageal squamous cell carcinoma." (PMID 38945960, 2024).
female infertility (1 paper, 2020). Diminished or absent ability of a female to achieve conception. "PHGDH was also shown to be major antigen for ovarian autoimmunity associated with female infertility." (PMID 32664979, 2020).
Glucose intolerance (1 paper, 2020). Glucose intolerance (GI) can be defined as dysglycemia that comprises both prediabetes and diabetes. "PHGDH is previously reported to be involved in the progression of glucose intolerance through serine biosynthesis in mice adipose tissues, while expression of TXNIP is increased in the presence of high glucose, which promotes oxidative stress and β-cell apoptosis." (PMID 32917208, 2020).
hepatoblastoma (1 paper, 2024). Hepatoblastoma (HB) is a malignant hepatic tumor and is the most common pediatric liver cancer. "Similarly, serine metabolism is crucial as it supports nucleotide and lipid synthesis by being produced from the glycolytic intermediate 3-phosphoglycerate via phosphoglycerate dehydrogenase (PHGDH), another enzyme frequently upregulated in hepatoblastoma." (PMID 39596558, 2024).
HIV-1 infection (1 paper, 2016). The type species of lentivirus and the etiologic agent of acquired immunodeficiency syndrome (AIDS). "The predicted models of PHGDH and PSAT1 interaction with other cellular gene products and pathways indicate a central role for these enzymes in helping the cell to adapt to metabolic changes in response to HIV-1 infection." (PMID 26821323, 2016).
Hypertension (1 paper, 2022). The presence of chronic increased pressure in the systemic arterial system. "Interestingly, differential methylation at multiple genes (SLC7A11, PHGDH, TXNIP, LOC100132354, CPT1A, SLC1A5) is associated with both AC (this study) and with hypertension." (PMID 34857913, 2022).
iron deficiency (1 paper, 2014). "In contrast, serine metabolism appears to be downregulated, since transcripts of genes coding for D-3-phosphoglycerate dehydrogenase (PGDH, EHI_060860), methionine γ-lyase 1 (MGL1, EHI_144610), and phosphoserine aminotransferase (PSAT, EHI_026360) were downregulated in iron deficiency." (PMID 25210888, 2014).
Juvenile onset (1 paper, 2022). Onset of signs or symptoms of disease between the age of 5 and 15 years. "Of note, a few patients with PHGDH or PSPH mutations prominently showed juvenile-onset peripheral neuropathy and mild neurodevelopment disorders." (PMID 36061210, 2022).